TNFAIP3 (TNF alpha induced protein 3)
Description:
Ubiquitin-editing enzyme that contains both ubiquitin ligase and deubiquitinase activities. Involved in immune and inflammatory responses signaled by cytokines, such as TNF and IL-1 beta, or pathogens via Toll-like receptors (TLRs) through terminating NF-kappa-B activity. Essential component of a ubiquitin-editing protein complex, comprising also RNF11, ITCH and TAX1BP1, that ensures the transient nature of inflammatory signaling pathways. In cooperation with TAX1BP1 promotes disassembly of E2-E3 ubiquitin protein ligase complexes in IL-1R and TNFR-1 pathways; affected are at least E3 ligases TRAF6, TRAF2 and BIRC2, and E2 ubiquitin-conjugating enzymes UBE2N and UBE2D3. In cooperation with TAX1BP1 promotes ubiquitination of UBE2N and proteasomal degradation of UBE2N and UBE2D3. Upon TNF stimulation, deubiquitinates 'Lys-63'-polyubiquitin chains on RIPK1 and catalyzes the formation of 'Lys-48'-polyubiquitin chains. This leads to RIPK1 proteasomal degradation and consequently termination of the TNF- or LPS-mediated activation of NF-kappa-B. Deubiquitinates TRAF6 probably acting on 'Lys-63'-linked polyubiquitin. Upon T-cell receptor (TCR)- mediated T-cell activation, deubiquitinates 'Lys-63'-polyubiquitin chains on MALT1 thereby mediating disassociation of the CBM (CARD11:BCL10:MALT1) and IKK complexes and preventing sustained IKK activation. Deubiquitinates NEMO/IKBKG; the function is facilitated by TNIP1 and leads to inhibition of NF-kappa-B activation. Upon stimulation by bacterial peptidoglycans, probably deubiquitinates RIPK2. Can also inhibit I-kappa-B-kinase (IKK) through a non-catalytic mechanism which involves polyubiquitin; polyubiquitin promotes association with IKBKG and prevents IKK MAP3K7-mediated phosphorylation. Targets TRAF2 for lysosomal degradation. In vitro able to deubiquitinate 'Lys-11'-, 'Lys-48'- and 'Lys-63' polyubiquitin chains. Inhibitor of programmed cell death. Has a role in the function of the lymphoid system. Required for LPS-induced production of pro-inflammatory cytokines and IFN beta in LPS-tolerized macrophages.
Synonyms: OTUD7C; A20; AIFBL1; AISBL; TNFA1P2
Tractability: PROTAC: ubiquitination databases record sites on it; its protein half-life has been measured.
Target class: Enzyme; Transferase
Gene: Protein-coding gene on chromosome 6 (137,866,383 to 137,885,836, forward strand). Ensembl gene ENSG00000118503.
Subcellular location: Cytoplasm; Nucleus; Lysosome; Cytoplasm (A20p50)
Subcellular location (Human Protein Atlas): Centrosome; Cytosol
Pathways (Reactome):
Signal Transduction: Regulation of TNFR1 signaling; TNFR1-induced NF-kappa-B signaling pathway; TNFR1-induced proapoptotic signaling
Immune System: NOD1/2 Signaling Pathway; Negative regulators of DDX58/IFIH1 signaling
Metabolism of proteins: Ovarian tumor domain proteases
Gene Ontology:
Molecular function: cysteine-type deubiquitinase activity; identical protein binding; K63-linked deubiquitinase activity; protease binding; protein binding; ubiquitin binding; ubiquitin-protein transferase activity; catalytic activity; DNA binding; enzyme binding; kinase binding; zinc ion binding
Biological process: cellular response to lipopolysaccharide; negative regulation of canonical NF-kappaB signal transduction; negative regulation of CD40 signaling pathway; negative regulation of endothelial cell apoptotic process; negative regulation of extrinsic apoptotic signaling pathway via death domain receptors; negative regulation of interleukin-1 beta production; negative regulation of interleukin-2 production; negative regulation of protein ubiquitination; negative regulation of smooth muscle cell proliferation; negative regulation of toll-like receptor 3 signaling pathway; positive regulation of protein catabolic process; protein K11-linked deubiquitination; protein K48-linked deubiquitination; protein K48-linked ubiquitination; protein K63-linked deubiquitination; response to molecule of bacterial origin; tolerance induction to lipopolysaccharide; B-1 B cell homeostasis; cellular response to hydrogen peroxide; negative regulation of B cell activation; negative regulation of bone resorption; negative regulation of inflammatory response; negative regulation of innate immune response; negative regulation of interleukin-6 production; negative regulation of osteoclast proliferation; and 21 more
Cellular component: extracellular exosome; nucleus; cytoplasm; cytosol; lysosome
Genetic constraint (gnomAD): Loss-of-function variants: 9 observed, 75.21 expected, observed/expected ratio (o/e) 0.12, 90% interval 0.071 to 0.21. The upper end of that interval is the gene's LOEUF score, 0.21, which puts it in group 1 of 6, group 1 being the genes least tolerant of losing a copy. Missense variants: 833 observed, 1,072.6 expected, observed/expected ratio (o/e) 0.78, 90% interval 0.73 to 0.82. Synonymous variants: 339 observed, 393.89 expected, observed/expected ratio (o/e) 0.86, 90% interval 0.79 to 0.94.
Cancer hallmarks: tumour promoting inflammation (suppresses); escaping immune response to cancer (suppresses)
Homologues: Orthologues: chimpanzee TNFAIP3 (99% identical), macaque TNFAIP3 (98% identical), rabbit TNFAIP3 (91% identical), dog TNFAIP3 (90% identical), guinea pig TNFAIP3 (90% identical), pig TNFAIP3 (89% identical), mouse Tnfaip3 (88% identical), rat Tnfaip3 (88% identical), zebrafish tnfaip3 (47% identical). Paralogues in human: OTUD7A (23% identical), OTUD7B (22% identical).
Diseases named in the same sentence as TNFAIP3 in open-access papers:
TNFAIP3 is named in the same sentence as 297 diseases in open-access papers, as found by Europe PMC text mining. Sharing a sentence is not in itself a finding about the gene and the disease. The quoted sentences say what the papers report.
psoriasis (72 papers, 2011 to 2025). An autoimmune condition characterized by red, well-delineated plaques with silvery scales that are usually on the extensor surfaces and scalp. "Psoriasis is a chronic inflammatory skin disease linked to immune dysregulation, notably involving TNFAIP3 (A20), a negative regulator of NF-κB signaling." (PMID 41226818, 2025). "Alt hough loss-of-function variants in TNFAIP3 are rare, they can predispose carriers to early-onset and severe psoriasis phenotypes." (PMID 41226818, 2025). "Among these, the A20 protein, encoded by the TNFAIP3 susceptibility locus shared by psoriasis and PsA, stands out." (PMID 41583484, 2025). "Genome-wide association studies have established TNFAIP3 polymorphisms as susceptibility loci for both psoriasis and PsA." (PMID 41583484, 2025). "Common variants mapped to TNFAIP3 are associated with a range of immune-mediated diseases including systemic lupus erythematosus, rheumatoid arthritis, psoriasis, multiple sclerosis, and Sjoegren's syndrome." (PMID 39241920, 2024). "TNFAIP3 is a known pathogenic gene in psoriasis and low TNFAIP3 expression in psoriatic skin is known to correlate with disease severity." (PMID 39337694, 2024). "The rs2230926 SNP in the TNFAIP3 gene, characterized by the G allele, was associated with an increased risk of psoriasis." (PMID 37569685, 2023). "The genes associated with psoriasis that encode regulators of the NF-kB pathway include TNFAIP3, TNFRSF1B, TNIP1, TRAF1IP2, and NF-κ-BIA." (PMID 37569685, 2023). "Genome-wide association studies have prominently linked various TNFAIP3 locus SNPs with autoimmune and inflammatory diseases including psoriasis, rheumatoid arthritis, systemic lupus erythematosus, Behcet’s disease, and Crohn’s disease." (PMID 36289219, 2022). "The SNP of TNFAIP3, the gene that encodes A20 protein and inhibits IL-17 signaling, was associated with risk for psoriasis." (PMID 34539646, 2021). "In psoriasis, however, only the effect of the TNFAIP3 rs610604 (G > T) and TNFAIP3 rs6920220 (G > A) polymorphisms have been evaluated." (PMID 33921427, 2021). "Subsequently, a study with 66 patients from the Netherlands diagnosed with psoriasis showed a significant association between the TNFAIP3 rs610604 polymorphism and response to UTK (ΔPASI at week 12)." (PMID 33921427, 2021). "The response to TNF blockers has been reported to be significantly associated with the TNFAIP3 TG haplotype (order of SNPs: rs2230926, rs610604) in psoriasis." (PMID 33287909, 2020). "Previously, it was shown that TNFAIP3 polymorphisms were associated with susceptibility to psoriasis." (PMID 32280718, 2020). "The importance of TNFAIP3 in reducing inflammation is underlined by the linking of TNFAIP3 genomic region polymorphisms with human autoimmune and inflammatory diseases, including RA, psoriasis, SLE, and type 1 diabetes." (PMID 32878252, 2020). "The results of this study support previous human studies as well as experimental studies in mice which clearly suggest the association of TNFAIP3 gene to psoriasis susceptibility and disease severity." (PMID 31120955, 2019). "Based on the finding that low TNFAIP3 expression is associated with increased susceptibility to inflammation, it can be concluded that decreased TNFAIP3 levels potentiates psoriasis susceptibility." (PMID 31120955, 2019). "It has also been noticed that TNFAIP3 gene single nucleotide polymorphisms (SNPs) are strongly associated with psoriasis through their inhibitory effect on cellular TNFAIP3 expression." (PMID 31120955, 2019). "On the other hand, TNFAIP3 overexpression in keratinocytes significantly represses cytokine production, suggesting a potential role of TNFAIP3 deficiency in the development of psoriasis via sensitization of keratinocytes to external stimuli." (PMID 31120955, 2019). "Analysis of TNFAIP3 haplotypes revealed that the psoriasis risk haplotype is different from other autoimmune diseases." (PMID 31120955, 2019).
psoriasis (continued). "One of those genes that has been described as a potent contributor to psoriasis pathogenesis is the tumor necrosis factor alpha-induced protein 3 (TNFAIP3) gene, which encodes TNFAIP3 protein, also known as TNF-α- inducible zinc finger protein A20." (PMID 31120955, 2019). "Nevertheless, Tnfaip3+/− mice are more susceptible to experimental psoriasis and atherosclerosis, but these specific symptoms are not commonly reported for HA20." (PMID 29515565, 2018). "These include interleukin 23 receptor (IL-23R) and tumor necrosis factor alpha-induced protein 3 (TNFAIP3), which have been implicated in the development of PsA more so than in psoriasis." (PMID 29364831, 2018). "In this regard, a recent report showed that TNFAIP3 gene single nucleotide polymorphisms (SNPs) were associated with response to TNFα blockade in psoriasis." (PMID 28658319, 2017). "Tumor necrosis factor-alpha-induced protein 3 (TNFAIP3) gene polymorphisms have been strongly associated with psoriasis susceptibility." (PMID 28658319, 2017). "TNFAIP3 gene SNPs are strongly associated with psoriasis, and at least one of these SNPs leads to reduced A20 expression in cell lines." (PMID 28658319, 2017). "SNPs in the TNFAIP3 gene, but also in other immune-regulatory genes including HLA-C, TNIP1/ABIN-1 and IL-23A have been associated to psoriasis and polymorphisms in the TNFAIP3 gene correlate to responsiveness to TNFα blockers in psoriasis patients." (PMID 26124703, 2015). "Further study has shown that the G allele of rs610604 in the TNFAIP3 gene correlates with a good response to TNF blockers in patients with psoriasis." (PMID 26046540, 2015). "Recent studies have revealed associations between TNFAIP3 polymorphisms and psoriasis, rheumatoid arthritis, systemic lupus erythematosus, type 1 diabetes mellitus, type 2 diabetes mellitus, Behcet's disease, and celiac disease." (PMID 25050625, 2014). "The SNP rs610604 in TNFAIP3 gene had previously been associated with predisposition to psoriasis and psoriatic arthritis." (PMID 24069534, 2013). "TNFAIP3 was also associated with psoriasis, a chronic inflammatory disease." (PMID 39125844, 2024). "It has been reported that several autoimmune and inflammatory disorders, including rheumatoid arthritis, systemic lupus erythematosus, psoriasis, inflammatory bowel disease, Crohn’s disease, Behcet’s disease, and type 1 diabetes, are associated with TNFAIP3 polymorphisms." (PMID 36064566, 2022). "In addition, TNFAIP3 gene polymorphisms were associated with responses to TNF antagonists in psoriasis." (PMID 32280718, 2020). "In this study, we found that TNFAIP3 expression was decreased in the PBMCs of psoriatic patients and confirmed its role in association with Th1 and Th17 cell differentiation and p38 activation in psoriasis using the IMQ-induced psoriasis-like dermatitis model." (PMID 32280718, 2020). "In summary, TNFAIP3 expression was downregulated in psoriasis, which might be associated with Th1 and Th17 cell differentiation and p38 activation." (PMID 32280718, 2020). "For example, the meQTL SNP rs629953 presents markedly different frequencies between AFB and EUB (DAF AFB 7.5% versus DAF EUB 62%), leading to variable population-level DNA methylation at TNFAIP3 (cg06987098), and has been associated with psoriasis susceptibility." (PMID 30563547, 2018). "In this study, we investigate how TNFAIP3, also known as A20, may regulate psoriasis susceptibility." (PMID 28658319, 2017). "We then performed qRT-PCR experiments on 18 independent skin samples (6 PP; 6 PN; and 6 NN) to assess the differential expression for lncRNAs G2608, G25746, and G36220 (a differentially expressed lncRNA (ENSG00000237499) in psoriatic skin and located within a psoriasis susceptibility locus TNFAIP3)." (PMID 25723451, 2015).
psoriasis (continued). "Furthermore, the TNFAIP3 gene is a susceptibility locus for several human inflammatory and autoimmune diseases, including inflammatory bowel disease, rheumatoid arthritis, psoriasis, lupus and type 1 diabetes." (PMID 24069342, 2013). "Several studies have suggested a role for TNFAIP3 polymorphisms in the susceptibility to complex autoimmune disorders, including rheumatoid arthritis (RA), psoriasis, systemic lupus erythematosus (SLE), Sjögren’s syndrome (SS), Crohn’s disease, and ulcerative colitis." (PMID 23555688, 2013). "Indeed, genetic polymorphisms of the TNFAIP3 gene have been described in several autoimmune diseases including rheumatoid arthritis, psoriasis, type 1 diabetes, inflammatory bowel disease, systemic lupus erythematosus (SLE), coronary artery disease and celiac disease." (PMID 32709905, 2020). "Therefore, the decreased TNFAIP3 expression in psoriasis might be associated with the increase in Th1 and Th17 cell numbers and their related cytokines." (PMID 32280718, 2020). "TNFAIP3 downregulation associated with Th1 and Th17 cell differentiation and p38 activation might contribute in part to the mechanism of immune dysfunction in psoriasis." (PMID 32280718, 2020). "Hence, the hypomorphic expression or function of TNFAIP3 may increment a susceptibility to psoriasis." (PMID 31120955, 2019). "The purpose of this study is to investigate how TNFAIP3 may regulate psoriasis susceptibility." (PMID 28658319, 2017). "SNPs in TLR2, TNF, SLC12A8, ZNF816A and TNFAIP3 genes were associated with 3-month response (measured as PASI90 and absolute PASI < 1) to Secukinumab and Ixekinumab in 19 psoriasis patients." (PMID 41153404, 2025). "In the blood of patients and mouse models for psoriasis, TNFAIP3 mRNA expression was reduced compared to unaffected individuals or control mice, respectively." (PMID 39125844, 2024). "The figure shows that after accounting for known up- and down-regulation expression patterns in psoriasis, only at the endpoint TNFAIP3, SHOC2 and HTR2A expression is retained." (PMID 39337694, 2024). "Polymorphisms in TNFAIP3 are associated with autoimmune diseases (systemic lupus erythematosus (SLE), RA, multiple sclerosis (MS), and psoriasis)." (PMID 38003572, 2023). "The results of our meta-analysis suggested that G allele of rs610604 polymorphisms in TNFAIP3 and A allele of rs17728338 polymorphisms in TNIP1 were considered to have an increased risk for psoriasis." (PMID 32398022, 2020). "TNFAIP3 had an important effect in several inflammatory diseases, such as systemic lupus erythematosus, inflammatory bowel disease, coeliac disease, and psoriasis." (PMID 32280718, 2020). "Tumour Necrosis Factor Alpha-Induced Protein 3 (TNFAIP3) and TNFAIP3 Interacting Protein 1 (TNIP1) are among them, and they were first discovered to be associated with psoriasis in 2009." (PMID 32398022, 2020). "To date, this is the first comprehensive study on the correlation between TNFAIP3 and TNIP1 polymorphisms and psoriasis vulnerability." (PMID 32398022, 2020). "mRNA expression levels of TNFAIP3 in the blood were significantly lower in patients with moderate and severe psoriasis (mean ± SD = 0.44 ± 0.25) compared with normal subjects (mean ± SD = 1.00 ± 0.82) (P < 0.01)." (PMID 32280718, 2020). "To investigate the role of TNFAIP3 in psoriasis, we collected PBMCs from patients with psoriasis and healthy controls." (PMID 32280718, 2020). "Of note, the TNFAIP3 mRNA expression levels in peripheral blood mononuclear cells (PBMCs) from patients with psoriasis were negatively correlated with disease severity in psoriasis vulgaris." (PMID 32280718, 2020). "To investigate the role of TNFAIP3 in the IMQ-induced psoriasis-like dermatitis model, we collected PBMCs from mice and detected TNFAIP3 mRNA expression by RT-PCR." (PMID 32280718, 2020). "Our findings indicated that rs610604 in TNFAIP3 and rs17728338 in TNIP1 gene polymorphisms were associated with psoriasis susceptibility." (PMID 32398022, 2020).